ENSG00000285733 (novel protein)
Gene: Protein-coding gene on chromosome 6 (169,419,969 to 169,702,047, reverse strand). Ensembl gene ENSG00000285733.
Genetic constraint (gnomAD): Loss-of-function variants: 23 observed, 22.26 expected, observed/expected ratio (o/e) 1.03, 90% interval 0.74 to 1.46. Missense variants: 219 observed, 212.76 expected, observed/expected ratio (o/e) 1.03, 90% interval 0.92 to 1.15. Synonymous variants: 91 observed, 77.35 expected, observed/expected ratio (o/e) 1.18, 90% interval 0.99 to 1.4.